NLRP3 (NLR family pyrin domain containing 3)
Diseases named in the same sentence as NLRP3 in open-access papers (continued):
Sharing a sentence is not in itself a finding about the gene and the disease.
leprosy (3 papers, 2019 to 2022). Leprosy is a chronic infectious disease affecting primarily the skin and peripheral nervous system. "NLRP3 overexpression is associated with high risk of lepromatousleprosy - Table II summarisesthe results of the relationship between leprosy spectrum groups and NLRP3inflammasome expression." (PMID 32130367, 2020). "We foundoverexpression of NLRP3 and caspases-4/5 biomarkers in the multibacillary forms(LL/BL and BB), particularly in the lepromatous form of leprosy." (PMID 32130367, 2020). "In this study, we investigated the role of the NLRP3 inflammasome-mediated pathway in theimmunopathological spectrum of leprosy by assessing the immunohistochemical expressionof inflammatory biomarkers in skin lesions." (PMID 32130367, 2020). "Our results demonstrate that the NLRP3 inflammasome is inactive in leprosy,suggesting immune evasion of M. leprae." (PMID 32130367, 2020). "The results reported here in allow us to conclude that, despite the overexpression ofNLRP3 and caspases-4/5 the lepromatous pole, the NLRP3 inflammasome does notactively participate in the innate immune response in leprosy." (PMID 32130367, 2020). "The present study presents relevant and original results regarding the participationof the NLRP3 inflammasome in the immunopathogenesis of leprosy." (PMID 32130367, 2020). "Strong expression of NLRP3 and inflammatory Caspases-4/5 were observed inlepromatous leprosy (lepromatous pole)." (PMID 32130367, 2020). "Besides contributing to explain the role ofthe NLRP3 inflammasome in the different immunopathological forms of leprosy, our datasuggest a possible mechanism of immune evasion of M. leprae." (PMID 32130367, 2020). "Indeed, our immunohistochemicalexpression results observed in the BB and LL/BL groups suggest the inactivation ornon-participation of the NLRP3 inflammasome and the immune evasion of M.leprae in this form of leprosy." (PMID 32130367, 2020).
lysosomal storage disorders (3 papers, 2020). "For example, the abnormal accumulation of cellular glycosaminoglycans in lysosomal storage disorders was strongly implicated in the pathogenic activation of NLRP3 inflammasome." (PMID 33488598, 2020). "Given that both primary and secondary storage substrates were required to initiate NLRP3 inflammasome‐mediated IL‐1β secretion, it is likely that several other lysosomal storage diseases, accumulating similar substrates, will share a similar mechanism of neuroinflammatory activation." (PMID 32057196, 2020).
Majeed syndrome (3 papers, 2017 to 2021). Majeed syndrome is a rare genetic multisystemic disorder characterized by the triad of chronic recurrent multifocal osteomyelitis, congenital dyserythropoietic anemia, and variable transient inflammatory dermatosis. "Recently, lipin-2 has been reported to regulate P2X7 receptor sensitization to limit overactivation of NLRP3 inflammasome, which may provide clues to better understand the molecular features that characterize the high IL-1β production found in Majeed syndrome patients with LPIN2 mutations." (PMID 29255148, 2017). "The last disease in this section is Majeed syndrome, which is an autosomal recessive disorder due to mutations in LPIN2 that encodes the protein LIPIN2, a negative regulator of NLRP3 inflammasome." (PMID 33042144, 2020). "Collectively, this provides support for Majeed syndrome being an NLRP3 inflammasomopathy." (PMID 33670882, 2021).
malignant pleural mesothelioma (3 papers, 2012 to 2022). A malignant neoplasm that arises from mesothelial cells in the pleura and shows a diffuse growth pattern. "Therefore, we hypothesize that NFE2L3, a novel biomarker in malignant pleural mesothelioma, may promote the differentiation of Th2 cells through the IL-2/STAT5/NLRP3 signaling pathway in multiple cancers." (PMID 35664314, 2022).
MRSA pneumonia (3 papers, 2020 to 2024). "The present study supports previous findings that immunotherapy targeting the NLRP3 inflammasome or IL‐1β signaling pathway may reduce the severity and improve the clinical outcomes in MRSA pneumonia secondary to IAV infection." (PMID 32697385, 2020). "However, the functions and mechanisms of the NLRP3 inflammasome in the severe MRSA pneumonia secondary to IAV infection remain unknown." (PMID 32697385, 2020). "However, the activity and function of the NLRP3 inflammasome in MRSA pneumonia secondary to IAV infection remain unclear." (PMID 32697385, 2020). "However, the link between the NLRP3 inflammasome and aggravated pathology of the lungs during MRSA pneumonia secondary to IAV infection remains unclear." (PMID 32697385, 2020).
Multiple Organ Failure (3 papers, 2023 to 2025). A progressive condition usually characterized by combined failure of several organs such as the lungs, liver, kidney, along with some clotting mechanisms, usually postinjury or postoperative. "Excessive NLRP3 inflammasome activation can induce dysregulated inflammation leading to multiple organ failure and death." (PMID 39840902, 2025). "Research has revealed the relationship between multiple organ failure and pyroptosis in SARS-CoV-2 infection, where the binding of ACE2 to the spike protein overactivates NLRP3, leading to the activation of the renin–angiotensin–aldosterone system and complement cascade." (PMID 38002346, 2023).
myasthenia gravis (3 papers, 2021 to 2022). Myasthenia gravis (MG) is a rare, clinically heterogeneous, autoimmune disorder of the neuromuscular junction characterized by fatigable weakness of voluntary muscles. "The NLRP3 inflammasome has also been shown to be involved in other rare neuromuscular diseases, such as Charcot–Marie-tooth (CMT) neuropathy and Myasthenia Gravis, which elicit symptoms of muscle weakness and muscle atrophy." (PMID 34199845, 2021).
Mycobacterium infection (3 papers, 2013 to 2025). Infections with bacteria of the genus Mycobacterium. "NLRP3 inflammasomes are multiprotein complexes which play a fundamental role in the body’s immune response to mycobacterial infection by providing a platform for caspase-1 activation." (PMID 40142455, 2025).
neuritis (3 papers, 2020 to 2024). A neuropathy arising from inflammation of one or more nerves. "Similarly, our study demonstrated that savinin had anti-neuritis effects via inhibiting MAPK and NF-κB, as well as NLRP3 pathways in LPS-induced mice, suggesting that savinin may contribute to the treatment of neurodegenerative disorders." (PMID 36838564, 2023).
optic neuritis (3 papers, 2020 to 2022). Optic neuritis is inflammation of the optic nerve, the nerve that carries the visual signal from the eye to the brain.The conditionmay cause sudden, reduced vision in the affected eye(s). "There were two patients with clubbing fingers (P9 and P12) and another one patient (P5) developing optic neuritis, both of which were uncommon manifestations of NLRP3-AID in previous reports." (PMID 35668534, 2022). "We also report that clubbing fingers and optic neuritis can be found in NLRP3-AID patients and expand the clinical spectrum of NLRP3-AID." (PMID 35668534, 2022). "Besides, we also found clubbing fingers and optic neuritis in some NLRP3-AID patients, which were not commonly mentioned in previous reports." (PMID 35668534, 2022).
oral lichen planus (3 papers, 2023 to 2024). Oral lichen planus is a chronic inflammatory oral condition of unknown aetiology characterized by T-cell-mediated chronic immune response and abnormal epithelial keratinization cycle. "Supporting evidence has shown that increased O-GlcNAcylation is associated with heightened expression of the NLRP3 inflammasome via the NF-κB signaling pathway in oral lichen planus (OLP)." (PMID 39742284, 2024). "The nucleotide-binding oligomerization domain (NOD)-like receptor (NLR) family pyrin domain-containing 3 (NLRP3) inflammasome has been reported to be highly expressed in oral lesions with the potential for malignant development such as oral lichen planus (OLP)." (PMID 38172822, 2024).
overactive bladder (3 papers, 2024 to 2026). Symptom of overactive detrusor muscle of the urinary bladder that contracts with abnormally high frequency and urgency. "Conditions like overactive bladder have been linked to systemic inflammation involving cytokines such as IL-1β and NLRP3 or oxidative stress parameters like increased MDA levels or depleted antioxidant levels." (PMID 40001926, 2025).
pancreatic diseases (3 papers, 2015 to 2023). "Activation of NLRP3 inflammasome depends on a complex regulatory mechanism, and its pro-inflammatory function plays an important role in pancreatic diseases." (PMID 37452057, 2023). "In this literature review, we summarize the activation mechanism of NLRP3 and analyze its role in each of the four typical pancreatic diseases." (PMID 37452057, 2023). "Several key factors support the improvement of pancreatic disease by Uro A. At first, Uro A inhibited ER stress and the TXNIP/NLRP3/IL-1β inflammation signal in β cells by modulating autophagy." (PMID 35745279, 2022).
polyarthritis (3 papers, 2015 to 2023). "Thus, when Nlrp3−/− or Casp1/11−/− mice were crossed with A20-deficient mice, they showed protection from spontaneous erosive polyarthritis (swelling and redness of all paws) compared to WT controls." (PMID 35455985, 2022). "However, NLRP3 deficiency protects A20-deficient mice from spontaneous polyarthritis." (PMID 35455985, 2022). "More recently, the NLRP3 inflammasome has been implicated in a murine model of RA, where deletion of A20 triggers spontaneous erosive polyarthritis through an increase in NLRP3 activation." (PMID 25975607, 2015). "Finally, a critical role for NLRP3 inflammasome in RA was clearly described in the spontaneous polyarthritis model, which develops in mice lacking the RA susceptibility gene A20/Tnfaip3." (PMID 35455985, 2022).
polymyositis (3 papers, 2022 to 2025). A rare idiopathic inflammatory myopathy characterized by symmetric proximal muscle weakness and elevated muscle enzymes. "This study was designed to investigate the role of the nucleotide-binding-domain -and leucine-rich repeat -containing (NLR) family, pyrin-domain-containing 3 (NLRP3) inflammasome in the pathogenesis of polymyositis (PM)." (PMID 35965334, 2022).
primary sclerosing cholangitis (3 papers, 2020 to 2023). "In the MDR2 knockout model of primary sclerosing cholangitis, intestinal dybiosis was associated with pronounced Nlrp3 inflammasome activation in the gut-liver axis." (PMID 35087852, 2021). "Nlrp3-deficient mice that underwent bile duct ligation (BDL) as a model for primary sclerosing cholangitis (PSC) had significantly less inflammation in acute (2 days) and chronic (28 days) injury in liver and kidney, hinting toward an important role of the inflammasome as well." (PMID 35087852, 2021). "NLRP3 overexpression was detected in reactive cholangiocytes in patients and murine models affected by primary sclerosing cholangitis; in vitro, NLRP3 activation stimulated the expression of IL-18 in cholangiocytes, with minimal effects on IL-1β." (PMID 37685870, 2023).
prostate tumor (3 papers, 2016 to 2024). "Considering the presence of many types of inflammatory cells, we analyzed the expression of some molecular components of the NLRP3 inflammasome pathway as it is also reported to be involved in the carcinogenesis of prostate tumors." (PMID 38791274, 2024). "In contrast to the NLRP3 expression, we found that NLRP12 protein is significantly higher in human prostate tumor tissues as compared to adjacent benign tissues." (PMID 28663562, 2017). "We further analyzed the clinical relevance of NLRP3 and NLRP12 in archival human prostate tumor specimens using IHC." (PMID 28663562, 2017). "Our observations support the idea that hypoxia in human prostatic tumors contributes to PCI, in part, by priming cells for the activation of NLRP3 and AIM2 inflammasome." (PMID 27058421, 2016).
pyoderma gangrenosum (3 papers, 2008 to 2025). An idiopathic, rapidly evolving, and severely debilitating disease occurring most commonly in association with chronic ulcerative colitis. "Mutations involving different autoinflammatory genes (MEFV, NLRP3, NLRP12, NOD2, LPIN2, and PSTPIP1) have been reported in syndromic HS [pyoderma gangrenosum, acne, and hidradenitis suppurativa (PASH) syndrome] as well as in pyoderma gangrenosum (PG), a prototypic neutrophilic dermatosis." (PMID 32425927, 2020).
scleroderma (3 papers, 2022 to 2024). Scleroderma is a rare autoimmune connective tissue disorder characterized by abnormal hardening of the skin and, sometimes, other organs. "In fact, the upregulation of secretion of at least 40 genes involved in the inflammasome pathway and NLRP3-mediated secretion of IL-1β and IL-18 has been demonstrated in scleroderma fibroblasts." (PMID 39203550, 2024). "Furthermore, both NLRP3 knockout (KO) mice and ASC KO mice showed resistance to bleomycin (BLM)-induced skin fibrosis, highlighting an important role of NLRP3 in scleroderma." (PMID 35396386, 2022). "The NLRP3 inflammasome and IL-1β are essential for scleroderma pathogenesis." (PMID 35396386, 2022). "Moreover, cultured monocytes derived from scleroderma patients showed increased TNF-α production, NLRP3 expression, and caspase-1 activation following B19V infection." (PMID 39203550, 2024). "Nevertheless, the role of pyroptosis executor gasdermin D(GSDMD), which is a downstream molecule of NLRP3 and is required for IL-1β release in some situations, has not yet been well elucidated in scleroderma." (PMID 35396386, 2022).
scrapie (3 papers, 2015 to 2022). A fatal disease of the nervous system in sheep and goats, characterized by pruritus, debility, and locomotor incoordination. "However, a recent in vivo study using NLRP3- or ASC-deficient mice inoculated with scrapie prions demonstrated that NLRP3 and ASC were not involved in prion pathogenesis." (PMID 28337127, 2017). "We then injected intracerebrally (i.c.)Nlrp3-/- and C57BL/6 wild-type mice with mouse-adapted scrapie prions (Rocky Mountain Laboratory strain, passage #6; RML6)." (PMID 25671600, 2015).
Seizure (3 papers, 2017 to 2025). A seizure is an intermittent abnormality of nervous system physiology characterized by a transient occurrence of signs and/or symptoms due to abnormal excessive or synchronous neuronal activity in the brain. "However, we did not found any significant difference of the rs4612666 (C>T), rs10754558 (C>G) and rs2027432 (C>T) for NLRP3 single-nucleotide polymorphisms between partial seizures patients and controls." (PMID 28503575, 2017). "In the present study, econazole effectively reduced TRPV5 expression in activated microglia following epileptic seizure and LPS stimulation, and further induced the disruption of AKT/NF‐κB activation, NLRP3 inflammasome complex assembly, and the production of proinflammatory cytokine IL‐18." (PMID 40708193, 2025).
Sézary syndrome (3 papers, 2021 to 2024). "Despite these abnormal patterns of expression, NLRP3 and AIM2 were equally expressed in the different groups, while NLRP1 expression was observed in Sézary syndrome skin compared to controls." (PMID 38397043, 2024). "Herein, to verify whether the expression of inflammasome components could be altered by Sézary syndrome, we assessed the expression of NLRP1, NLRP3, AIM2, IL-1B and IL-18 by immunohistochemistry in the epidermal and dermal layers of skin from SS patients." (PMID 36902104, 2023). "To evaluate whether NLRP3 may regulate IL-4 expression in malignant CD4+ T cells, we used the HTB-176 cell line isolated from the peripheral blood of a patient with Sézary syndrome." (PMID 34220814, 2021).
Still’s disease (3 papers, 2021 to 2024). "Furthermore, NS1 protein also induces expression of IL-1β and IL-18 through activation of caspase-1-associated NLR family pyrin domain containing 3 NLRP3 inflammasome in peripheral blood mononuclear cells (PBMCs) from Still’s disease patients." (PMID 39203550, 2024). "However, different from other inflammatory diseases such as systemic Juvenile Idiopathic Arthritis (sJIA), increased Ferritin was uncommon in NLRP3-AID (1/9)." (PMID 35668534, 2022).
streptococcal infection (3 papers, 2019 to 2022). Any of the several infectious disorders caused by members of streptococcus, a genus of gram positive bacteria belonging to the family Streptococcaceae. "PLY, by triggering cell death and evading several host defense mechanisms, appears to directly increase the level of NLRP3 during streptococcal infection." (PMID 35111047, 2021). "Although NLRP3 and AIM2 participate in IL-1β release by bmDCs and MΦ following infection by GBS and S. pneumoniae, the implication of NLRP1 and NLRC4 have not yet been described following streptococcal infection." (PMID 31262357, 2019).
thrombotic disease (3 papers, 2023 to 2025). The formation of a blood clot in the lumen of a vessel or heart chamber; causes include coagulation disorders and vascular endothelial injury. "A deeper understanding of the relationship between the NLRP3 inflammasome and thrombosis is important for elucidating the pathogenesis of thrombotic diseases and developing new therapeutic strategies." (PMID 40520933, 2025). "In a nutshell, NETosis plays an important role in the pathogenesis of thrombotic disorders through its upstream mediator, the NLRP3 inflammasome." (PMID 38067137, 2023). "Furthermore, the NLRP3 inflammasome also serves as a mediator of NETosis and thrombosis, highlighting the importance of NLRP3 inhibition as a novel therapeutic approach for thrombotic diseases." (PMID 38654328, 2024). "Therefore, future preclinical and clinical studies aimed at identifying and validating NLRP3 inhibition as a novel therapeutic intervention for thrombotic disorders are imperative." (PMID 38067137, 2023). "Therefore, it is conceivable that the inhibition of NLRP3-mediated NETosis can pave the path for developing novel therapeutic approaches for several thrombotic disorders." (PMID 38067137, 2023). "Since NLRP3 activation plays an important role in the NET release, it is highly anticipated that their activation will contribute towards the onset of various thrombotic disorders." (PMID 38067137, 2023).
thymoma (3 papers, 2014 to 2022). A neoplasm arising from the epithelial cells of the thymus. "Mice lacking NLRP3 were far more receptive to thymoma regression upon treatment with Gem or 5FU as compared to WT mice." (PMID 25071785, 2014).
allergic conjunctivitis (2 papers, 2020 to 2026). "Besides the canonic effect, TR has been applied in several inflammatory disease including bronchial asthma, atypical dermatitis, allergic conjunctivitis, and hypertrophic scars by directly binding to the NACHT domain of NLRP3 to suppress the of NLRP3 inflammasome." (PMID 32754591, 2020).
anaplastic thyroid cancer (2 papers, 2021 to 2024). "The acetylase inhibitor SI-2, usually used as an antitumor reagent for anaplastic thyroid carcinoma 31977311, specifically inhibits NLRP3 inflammasome activation by disrupting the interaction between NLRP3 and ASC and by blocking ASC speck formation." (PMID 34064909, 2021). "In this study, we found that ibuprofen induces pyroptosis in anaplastic thyroid cancer cells via the NLRP3/ASC/GSDMD pathway, which activates the NLRP3 inflammasome and cleaves GSDMD in vitro and in vivo." (PMID 37999895, 2024).
anterior uveitis (2 papers, 2022 to 2025). Inflammation of the iris and anterior chamber of the eye. "Apart from Behçet’s disease, cryopyrin-associated periodic syndrome, a group of inherited autoinflammatory disorders caused by NLRP3 mutations, shows ocular symptoms, including anterior uveitis." (PMID 35836195, 2022).